LIN28A (lin-28 RNA binding posttranscriptional regulator A)
Diseases named in the same sentence as LIN28A in open-access papers (continued):
Sharing a sentence is not in itself a finding about the gene and the disease.
cancer (206 papers, 2008 to 2025). A tumor composed of atypical neoplastic, often pleomorphic cells that invade other tissues. "Loss of cancer differentiation from luminal-like to stem-like is mediated by the activation of stem cell transcription factors (scTF) such as LIN28A, NANOG, POU5F1 and SOX2." (PMID 38595814, 2024). "Through gain-or loss-of-function studies in various cancer cell lines and mouse models, Lin28A/B has been shown to promote tumor growth, invasion and metastasis." (PMID 34572067, 2021). "LIN28A is a pluripotent factor and highly conserved RNA-binding protein associated with neurodevelopment and the pathogenesis of various advanced cancers." (PMID 34239534, 2021). "The negative regulators of let-7a biogenesis including Lin28a, Lin28b and hnRNP A1 are associated with cancer formation." (PMID 33669264, 2021). "Abnormal LIN28A activation has been identified in multiple cancers and associated with advanced cancer grade and poor prognosis." (PMID 32333719, 2020). "Numerous studies have pointed out that the highly expressed Lin28A is association to advanced human malignancies, and Lin28A mainly plays an important role in promoting cancer development through let-720-23." (PMID 32398961, 2020). "Reactivation of either LIN28A or LIN28B is a hallmark of many human cancers where the expression of these proto-oncogenes is typically mutually exclusive." (PMID 28400788, 2017). "First, LIN28B overexpression in human cancers has been frequently associated with human tumorigenesis compared with LIN28A." (PMID 27095948, 2016). "LIN28A is a stem cell factor that was first discovered as a regulator of development, and it has since been implicated in multiple aggressive cancers." (PMID 25638158, 2015). "High levels of LIN28A/LIN28B proteins are associated with many cancer biological behaviors and poor prognosis." (PMID 26123544, 2015). "In addition, human LIN28A/B were upregulated in a spectrum of tumors (~15%), and the elevated expression of them was often associated with increased cancer aggression and poor prognoses." (PMID 35102250, 2022). "Lin28A and Lin28B are aberrantly expressed in a plethora of tissue malignancies, and activation of either Lin28A or Lin28B is responsible for the global post-transcriptional downregulation of let-7 miRNAs in many cancers, which is associated with advanced tumor stages and poor patient outcomes." (PMID 34572067, 2021). "The RNA-binding protein LIN28A has been reported to be associated with poor prognosis and often up-regulated in a variety of malignant tumors and facilitate cancer metastasis." (PMID 33665193, 2021). "Abnormal AS is now regarded as a valuable indicator of carcinogenic processes and prognosis, as well as a potential target of treatment in several types of cancer.Not only is it a valuable diagnostic marker of ETMRs, LIN28A overexpression can be functionally significant as well." (PMID 32971786, 2020). "The LIN28/let-7 pathway is directly implicated in cancer using genetically engineered mouse models where ectopic LIN28A and/or LIN28B expression cause and/or enhance progression of neuroblastoma, Wilms tumor, mast cell leukemia, hepatocellular carcinoma, and colorectal adenocarcinoma." (PMID 30057901, 2018). "In contrast to this result, loss of ZCCHC11 via siRNA on its own was sufficient to cause regression of established LIN28A-positive tumor xenografts to a similar level as LIN28A knockdown, raising doubts on TUTase redundancy in let-7 repression in LIN28A-positive human cancer cells." (PMID 28400788, 2017). "The RNA-binding protein LIN28A is an oncogenic factor being overexpressed in various cancer types occurring in the brain, ovary, breast, intestine, or colon." (PMID 40680886, 2025). "LIN28A promotes genes involved in ribosome biogenesis and dysregulation of ribosomal proteins is described in different cancer types supporting the proliferative behavior." (PMID 40680886, 2025).
cancer (continued). "Cancers with high LIN28A expression generally show a poor prognosis, and LIN28A suppression by exogenous let-7 slowed tumor growth in mice." (PMID 38836981, 2024). "Lin28A/B are primarily expressed in stem and progenitor cells, play a crucial role in diverse cellular processes 7,8,11-18 and are overexpressed in various cancer types, acting as oncogenes (for reviews, see 5,22,24,40,41)." (PMID 39113694, 2024). "LIN28 consists of two paralogs, LIN28A and LIN28B, which are overexpressed in approximately 15% of human cancers, with overexpression generally associated with a poor prognosis." (PMID 38329136, 2024). "JUN is known to promote cancer cell proliferation and Lin28A is a known oncogene that promotes cell cycle progression in cancer cells." (PMID 38000389, 2024). "This study reveals the molecular basis for mono- versus oligo-uridylation by TUT7/4, as determined by the presence of LIN28A, and thus their mechanism of action in the regulation of cell fate and in cancer." (PMID 39054354, 2024). "LIN28A is also known for its roles in epithelial to mesenchymal transition and contributes to tumor malignancies in various cancer types." (PMID 36509142, 2023). "Genes that have been shown to play a role in this dysregulation include PIWIL1, LIN28A and LIN28B, and have been associated with poorer patient outcomes and more aggressive cancer subtypes." (PMID 36980876, 2023). "This action has been demonstrated in embryonic stem cells, suggesting a significant role of LIN28A in inhibiting cell differentiation through miRNAs in stem cells and certain types of cancer." (PMID 37559082, 2023). "Another important set of genes that drive the ncRNA-influenced development of embryonic cells and cancer cells includes LIN28A and LIN28B." (PMID 36980876, 2023). "To confirm that our Lin28 inhibitors can block Lin28A activity in cancer cells, we have used the IGROV1 cell model that expresses Lin28A but not Lin28B protein." (PMID 36428779, 2022). "The roles of Lin28A and Lin28B in cancer development and progression have been elucidated over the last decade." (PMID 36230562, 2022). "This is a likely mechanism by which TTP-mediated Lin28a repression inhibits the growth of human cancer cells." (PMID 35806250, 2022). "Ultimately, USP28 induces the tumorigenic function of LIN28A and enhances the viability and migration of cancer cells, increasing LIN28A-mediated tumor progression." (PMID 35806250, 2022). "Elevated expression of Lin28A/B enhances de novo fatty acid synthesis to promote cancer progression via SREBP-1." (PMID 34572067, 2021). "Among them, LIN28A and HMGA2 have been implicated in cancer initiation, progression, and chemoresistance, and both serve as markers of CSCs." (PMID 34572843, 2021). "How hypoxia differentially regulates the expression of LIN28A at different levels is a fascinating question, and the significance of this regulation in cancer progression is an attractive topic." (PMID 33665193, 2021). "It is also undetected if the expression of LIN28A gene at the mRNA level and the protein level is parallel in cancer cells under hypoxia." (PMID 33665193, 2021). "The global underexpression of the let-7 miRNA family observed in many cancers is affected by the RNA binding proteins LIN28A/B, which block let-7 biogenesis and consequently the TS function of all let-7 family members." (PMID 34771690, 2021).
cancer (continued). "The RNA-binding protein Lin28 (Lin28a) is an important pluripotency factor that reprograms translation and promotes cancer progression." (PMID 33742080, 2021). "This RNA‐PROTAC binds selectively to Lin28 in vitro, and suppressed levels of Lin28A in two cancer cell lines in ubiquitin‐dependent fashion." (PMID 33108679, 2021). "Although many studies have examined the interaction between Wnt and Lin28A in mammals, primarily as it relates to cancer, a role for this interaction in PGC formation has not been reported." (PMID 33443086, 2021). "In this study, we were able to demonstrate for the first time that hypoxia induced the expression of LIN28A in cancers." (PMID 33665193, 2021). "Underexpression of the let-7 miRNA family, observed in many cancers, is effected by the RNA binding proteins LIN28A/B that block pre-let-7 (inactive) processing to mature let-7 and their TS function." (PMID 34771690, 2021). "Highly expressed RBPs LIN28A can act as a potential oncogenic factor to promote tumorigenesis, progression, and metastasis in various human cancers." (PMID 34868981, 2021). "SUMOylation of LIN28A aggravates its inhibition of let‐7 maturation, resulting in a stark reduction in let‐7, which promotes cancer cell proliferation, migration, invasion, and tumor growth in vivo." (PMID 32333719, 2020). "SUMOylation of Lin28A is regulated in response to cancer cellular stresses such as hypoxia and chemotherapy drug treatment, which have implications in cancer prognosis and therapy." (PMID 32333719, 2020). "LIN28A was reported as a regulator of self-renewal capacity in cancer stem cells, cellular metabolism, and the cell cycle through binding and repression of let-7 microRNAs." (PMID 32971786, 2020). "SUMOylated LIN28A aggravated cancer cell proliferation, migration, invasion, malignancy transformation, and tumor growth in vivo, thereby modulating tumor progression." (PMID 32333719, 2020). "In particular, LIN28A is re‐activated in overall frequency ~ 15% primary human tumors and human cancer cell lines, and promotes malignancy through down‐regulation of let‐7s." (PMID 32333719, 2020). "LIN28A is a conserved RNA‐binding protein that inhibits the biogenesis of let‐7 microRNAs, thus promoting cancer progression." (PMID 32333719, 2020). "Our findings suggested that Lin28A and Lin28B are promising biomarkers, and the detection of Lin28A and Lin28B expression in cancer patients is of potential value for monitoring patients’ survival." (PMID 30976203, 2019). "The mammalian homologs of Lin-28, Lin28 (also called Lin28A) and Lin28B, are promising cancer biomarkers." (PMID 30976203, 2019). "Here we identify an essential function of Lin28a factor during the early stages neural crest development, which is consistent with its role as a regulator of pluripotency in stem cells and cancer." (PMID 30520734, 2018). "A high Lin28A or Lin28B and low let-7 expression pattern is found in approximately 15% of human cancers." (PMID 29301498, 2018). "While stable expression of Lin28 in cancer cells with low Lin 28 levels significantly reduced their sensitivity to paclitaxel, LIN28A knockdown in T47D cells effectively sensitized them to the drug." (PMID 28400788, 2017). "In cases where a specific cancer type expresses both LIN28A and LIN28B, these tend to occur in distinct tumor subtypes." (PMID 28400788, 2017). "Functionally, one gene did catch our attention: LIN28A is a potent pluripotency factor and a marker of cancer stem cells." (PMID 29088719, 2017). "It is now evident that Lin28a is an important oncogene in tumorigenesis and an emerging maker of cancer stem cells." (PMID 27881476, 2017). "To further inspect the direct role of Sfpq in controlling miRNA targeting in cells, we focused on a particular known let-7a target—the oncogene Lin28A, also known as Lin-28 homolog A, which regulates the self-renewal of stem cells and cancer stem cells." (PMID 29084942, 2017).
cancer (continued). "Lin28A protein is a RNA-binding protein that regulates the biogenesis of several miRNAs (e.g., let-7d miRNA) and has important roles in cancer, tissue regeneration and the self-renewal of stem cells." (PMID 28912471, 2017). "Previous studies have reported that LIN28A overexpression induces cancer cell migration and invasion." (PMID 28587210, 2017). "In cancer cells, the embryonic function of LIN28A/LIN28B is subverted to induce a metabolic shift from oxidative phosphorylation to glycolysis." (PMID 28400788, 2017). "As compared to cells expressing a low level of LIN28A, T47D cancer cells with high expression of Lin28 was shown to be more resistant to paclitaxel." (PMID 28400788, 2017). "A recent study showed that LIN28A expression was positively correlated with a higher percentage of ALDH1 positive cancer cells and is important in maintaining these cells." (PMID 28400788, 2017). "The activation of LIN28A/B occurs in several different primary human tumors and plays an important role in cancer progression and metastasis, involving stemness through the negative regulation of the maturation of let-7 microRNA (miRNA) family members." (PMID 27095948, 2016). "KLF4 and LIN28A, which are known as important cancer stem cell factors, were also increased in expression." (PMID 26675549, 2016). "These researches imply the importance to distinguish the expression and functions of both Lin28A and Lin28B in certain cancer types." (PMID 27793004, 2016). "In particular, the expression of CCDN1 was found to be regulated by LIN28A via the inhibition of let-7 miRNA biogenesis in cancer cells." (PMID 26057471, 2015). "Since myc is one of the target genes of let-7, let-7-mediated inhibition of myc thus inhibits the crosstalk of hallmarks of cancers; LIN28A/LIN28B, of course, has the opposite effect." (PMID 26123544, 2015). "Over-activation of LIN28A or LIN28B is one mechanism by which cancer cells can eliminate let-7 microRNAs and allow for increased expression of pro-oncogenic signals." (PMID 23846349, 2013). "The identification of pluripotency factors such as SOX2, OCT4, KLF4 and LIN28A in human cancer suggests a close relationship between tumor formation and the process of reprogramming mature cells to a more primitive type." (PMID 23846349, 2013). "To further evaluate whether the suppressive effects of Ln268 are specific to Lin28-positive cancer cells, we compared cell growth rates of DuNE (Lin28b-positive line) and Du145 (Lin28b-negative line), both of which are Lin28a-negative." (PMID 39800739, 2025). "The LIN28/let‐7 axis has been reported to facilitate aerobic glycolysis to promote cancer progression.[14b] In this study, PIWIL2 overexpression in HaCaT cells induced LIN28 upregulation, particularly that of LIN28A, and PDK1, which also were observed in HCBC stably transfected with PIWIL2 or E6." (PMID 39499767, 2024). "Lin28A and Lin28B are mutually exclusive in expression in human cancer cell lines." (PMID 36230562, 2022). "Both Lin28A and Lin28B play important roles in cancer development and progression." (PMID 36230562, 2022). "Indeed, a comprehensive analysis of Lin28A and Lin28B expression over a panel of 527 human cancer cell lines revealed that the paralogs are overexpressed in roughly 15% of cancer types." (PMID 36230562, 2022). "Furthermore, Uro-A treatment resulted in the upregulation of let-7a and repression in the protein expression of Lin28a, Zcchc11, and Sp-1, a transcriptional factor overexpressed in most cancer and a target for Lin28a activity." (PMID 34164422, 2021). "LIN28A/B are RNA binding proteins that negatively regulate let-7 biogenesis and act as proto-oncogenes responsible for the post-transcriptional downregulation of let-7 observed in many cancers." (PMID 34771690, 2021). "As a control, elevated LIN28A protein evidently promoted cancer growth both in vitro and in vivo." (PMID 33665193, 2021).
cancer (continued). "However, it is undetermined if hypoxia promotes cancer metastasis by means of regulating the expression of LIN28A." (PMID 33665193, 2021). "LIN28A is a master oncogene and promotes both metastasis and proliferation of cancer cells." (PMID 33665193, 2021). "LIN28A is an RNA-binding protein that is overexpressed in many cancers." (PMID 34572725, 2021). "By direct association with the mRNAs of both SREBP-1 and SCAP, Lin28A/B enhances the translation and maturation of SREBP-1, which, in turn, accelerates metabolic conversion of saturated and unsaturated fatty acids and protects cancer cells from lipotoxicity." (PMID 34572067, 2021). "Considering that LIN28A is associated with malignant cancer and poor prognosis, our data raise the hypothesis that LIN28A might affect the activities of certain ribosomal subunits through protein-protein interactions, leading to a cancer-prone state." (PMID 34816099, 2021). "RNA-binding protein LIN28A is often elevated in various cancer types." (PMID 33665193, 2021). "Furthermore, the role of LIN28A in regulating splicing and gene expression programs has been investigated in cancer." (PMID 32971786, 2020). "In summary, our findings shed light on a novel mechanism that SUMOylation of Lin28A is required for activation of the Lin28A‐let‐7 pathway in response to cancer cellular environment stresses, which could have implications for cancer prognosis and therapy." (PMID 32333719, 2020). "Taken together, our data reveal a novel mechanism, by which SUMOylation of LIN28A may be essential for activation of the LIN28A‐let‐7 pathway in cancer cells in response to stresses that have guiding significance for clinical treatment of cancer." (PMID 32333719, 2020). "Overexpression of Lin28A or Lin28B suggests poor prognosis for cancer patients." (PMID 30976203, 2019). "Lin28A (one human homolog of lin28) is expressed in embryonic cells and cancer cells." (PMID 30602712, 2018). "Notably, these cancers exhibited the expression of pluripotency-related proteins, Sall4 and Lin28a, independently of OSKM transgene expressions." (PMID 29802314, 2018). "Clinical relevance of LIN28A/LIN28B expression in human cancers." (PMID 28400788, 2017). "Both Lin28a and Lin28b are misexpressed in a number of tumor and cancer cells." (PMID 27881476, 2017). "Furthermore, LIN28A expression was shown to promote adherence and migration in cancer cells and is correlated with tumor invasiveness." (PMID 28400788, 2017). "Thus, studying the systems where Lin28a is overexpressed is of utmost importance to understand its various roles in cancer biology." (PMID 27881476, 2017). "Numerous studies have shown that both Lin28A and Lin28B are over-expressed in many cancer types." (PMID 27793004, 2016). "Additionally, RNA binding protein Lin28A and Lin28B interacts with different target mRNAs in cancer cells." (PMID 27793004, 2016). "Although it was demonstrated that either Lin28A or Lin28B is over-expressed in malignant tumors and promotes cancer progression, few researches detected the expression and function of both oncogenes in human malignant tumors at same time." (PMID 27793004, 2016). "Interestingly, overexpression of mammalian LIN28A and LIN28B is often associated with malignant tumors in human." (PMID 27296804, 2016). "It has been reported that LIN28A expression are reactivated in human cancers." (PMID 26910839, 2016). "Similar to its role in reprogramming somatic cells to iPSCs, an elevated expression of Lin28a/b might also be important in the formation of cancer stem cells (CSCs)." (PMID 23939427, 2013). "Furthermore, it remains to be verified which of the huge number of novel mRNA targets are indeed directly regulated by Lin28a/b and what are their impact on stem cell maintenance/differentiation, development, metabolism and cancer." (PMID 23939427, 2013).